FOXO1 (forkhead box O1)
Diseases named in the same sentence as FOXO1 in open-access papers (continued):
Sharing a sentence is not in itself a finding about the gene and the disease.
cancer (continued). "We, therefore, speculate that FOXO1 may act in a cancer-promoting manner in certain cancer cell types by activating MDM2 transcription." (PMID 38519029, 2024). "FOXO1 might play a role as an oncogenic gene in LGGand OV, while playing a cancer suppressor role in KIRC." (PMID 38716982, 2024). "FOXO1 is a well-recognized tumor suppressor gene that can inhibit the proliferation, invasion, and migration abilities of various malignant tumor cells (such as hepatocellular carcinoma, colorectal cancer, gastric cancer, prostate cancer, etc.), while promoting their apoptosis." (PMID 39021599, 2024). "FOXO1 has been reported to play an important role in human cancers." (PMID 39684225, 2024). "However, the functions and processes of FOXO1 in different types of cancers remainincompletely understood." (PMID 38716982, 2024). "FOXO1 is mainly involved in glucose metabolism, insulin signaling, and lipid synthesis, while FOXO3 is more associated with anti-stress responses, longevity, and cancer." (PMID 39021599, 2024). "Throughmultiple public platforms, a pan-cancer analysis of FOXO1 was conducted toobtained FOXO1 expression profiles in various tumors to explore the relationshipbetween FOXO1 expression and prognosis of these tumors and to disclose thepotential mechanism of FOXO1 in these tumors." (PMID 38716982, 2024). "Additionally, the G9a‐specific inhibitor BIX‐01294 can suppress the methylation of FOXO1, thereby modulating cancer cell proliferation and apoptosis, exerting anticancer effects." (PMID 39184862, 2024). "Finally, we examined the correlation between the expression of FOXO1 and PFIacross various types of cancer." (PMID 38716982, 2024). "This is the first study to research the expression and mechanism of FOXO1 inpan-cancer." (PMID 38716982, 2024). "FOXO1 may be a potential target for epigenetic diagnosis or treatment of cancer in the future and may serve as a potential marker for assessing cancer prognosis." (PMID 36830954, 2023). "Additionally, we also identified several genes, including FOXS1, FOXP3, and FOXD2, showed elevated expression in a variety of tumors, while FOXF1, FOXP2, and FOXO1 were downregulated in the majority of cancers." (PMID 37401400, 2023). "Given the critical role of cancer stem cells in promoting cancer progression, we examined the impact of FOXO1 inhibition with AS1842856 (a cell‐permeable small molecule that directly binds to unphosphorylated FOXO1 protein to block transcriptional regulation) on BBC and GBM cell viability." (PMID 36602390, 2023). "Similarly, in this study, we observed a significant increase in FOXO1 expression in cancer cell lines exposed to different doses of our polyphenolic mixture." (PMID 36835085, 2023). "Previously, miR-196a was proven to enhance cancer cell proliferation by targeting FOXO1 and HOXA5." (PMID 38067033, 2023). "The differences may be due to post-translational modifications of FOXO1, e.g., acetylation, which promotes autophagy, affecting the survival of cancer cells." (PMID 36830954, 2023). "FoxO1 is a well-known key transcription factor that regulates cellular processes involved in glucose metabolism, apoptosis, oxidative stress, DNA damage repair, and cancer development." (PMID 37740216, 2023). "Moreover, FOXO1 has also been demonstrated to oversee other critical aspects of cancer, including the regulation of angiogenesis." (PMID 37894854, 2023). "Perhaps FOXO1 promotes the silencing of apoptotic genes in these cancers." (PMID 36602390, 2023). "The role of FOXO1 in cancer and apoptosis is becoming increasingly complex." (PMID 36602390, 2023).
cancer (continued). "It is important to note that the capacity of FOXO proteins, in particular FOXO1 and 3 to promote stem cell maintenance might also be relevant for cancer stem cells (CSCs)." (PMID 37891184, 2023). "One of the processes regulated by this SIRT1/FoxO1 pathway is autophagy, which has emerged as a crucial and controversial mechanism that can play a dynamic tumor-suppressive or promoting role depending on the cancer context and cellular type." (PMID 36771230, 2023). "This could explain that the spectrum of cancer types in the triple FOXO1, 3, and 4 knockout mice are limited to a few lineages." (PMID 37891184, 2023). "Some studies have demonstrated that miR-182 may act on the proliferation, migration, and invasion of many cancers through suppression of FOXO1." (PMID 35627108, 2022). "Moreover, it has been shown that the inhibition of the expression of E6 and E7 in Ca Ski cells recovers the expression of FOXO1, leading to apoptosis and to a reduction in the proliferation of cancer cells." (PMID 36497200, 2022). "Several therapies antagonizing FOXO1 were under research in cancers and metabolic disorders." (PMID 36424620, 2022). "With the increase of the proportion of MDS blast cells, the expression of FOXO1 decreased significantly, suggesting that FOXO1 gene may play an anti-cancer role in MDS." (PMID 36290822, 2022). "Thus, FOXO1 deacetylation promotes cell autophagy, but inhibiting the autophagy level of cancer cells can enhance their chemotherapeutic sensitivity." (PMID 35126526, 2022). "Thus, the downregulation of FOXO1 expression leads to dysregulation of cell cycle regulators which induce cell proliferation and play important role in the formation of cancer." (PMID 36539739, 2022). "The effect of FOXO1 in different cancers is also controversial." (PMID 35609322, 2022). "Cancers can also occur with enhanced degradation of forkhead box O1 (FOXO1) by Skp2." (PMID 36499442, 2022). "In addition, activated AMPK leads to the in the upregulation of FOXO1 and induces autophagy in cancer cells, promoting EMT." (PMID 35770085, 2022). "We further examined whether the most abundant genes in the top altered pathways upon CAP exposure were involved in cancer stemness regulation and whether these genes and canonical genes controlling cancer stemness could be regulated by FOXO1." (PMID 35637961, 2022). "FOXO1 is downregulated in a variety of cancers and is considered to be a tumor suppressor." (PMID 34368119, 2021). "FoxO1 was reported to directly regulate autophagy in a transcription-independent manner, and acetylated FoxO1 could induce autophagy by interaction with autophagy-related protein 7 in cancer cells." (PMID 34522203, 2021). "In addition to known cachexia genes such as FOXO1, novel genes from muscle, including PPP1R8 and AEN correlated with cancer weight loss." (PMID 33923976, 2021). "FOXO1, as a target gene, is regulated by some miRNAs in human cancers, such as miR-9 and miR-135a." (PMID 34035814, 2021). "Moreover, activation of MAPK/ERK has been reported to impair autophagy process by promoting the degradation of Fork head Box O1 (FOXO1), a protein associated with maintenance of autophagic flux in cancer cells." (PMID 34488902, 2021). "Based on our findings that USP7 deubiquitinated H2BK120ub1 and recruited the PRC2 complex to suppress the transcription of FOXO1, we postulated that the tumorigenic effect of USP7/EZH2-FOXO1 signaling pathway could be extended to a broader scope of cancers." (PMID 33849069, 2021). "In addition, FOXO1 actively participates in the migration, invasion, and metastasis of cancer cells in specific cancers or diseases." (PMID 34635635, 2021). "The results showed that FOXO1 levels were decreased in many cancer types." (PMID 32047567, 2020).
cancer (continued). "However, the functional consequence of the ERK/FOXO1-regulated Ets1 on the induction of angiogenesis and metastasis has yet to be confirmed in cancer cells." (PMID 32372224, 2020). "These contrasting findings may reflect the deregulation of normal FOXO1 control and function in cancer cells." (PMID 32372224, 2020). "Furthermore, miR-132, miR-223 and miR-27a can induce proliferative arrest and cancer cell death through FOXO1 and FOXO3." (PMID 32372224, 2020). "Reactivate the apoptotic function of FOXO1 at the late stages of the cell cycle may improve the anti-cancer efficacy of BI2536." (PMID 32704044, 2020). "In light of these results and their strong literature support, we hypothesized that expression levels of FOXO1, together with predicted TF partners could be a potential readout to interrogate clinical cancer data." (PMID 31913281, 2020). "Therefore, restoring the pro-apoptotic functions of FOXO1 in cancerous cells would be of great interest for the treatment of human cancers." (PMID 32704044, 2020). "Given that inactivation of FOXO1 has been reported in many types of human cancer, we sought to investigate whether restoration of the pro-apoptotic activity of FOXO1 may be used as a new promising strategy for cancer treatment." (PMID 32704044, 2020). "The FOXO1 protein is polyubiquitinated by E3 ligases such as S-phase kinase-associated protein 2 (SKP2) and mouse double minute 2 homolog (MDM2), and targeted for protein degradation in human primary tumors and cancer cell lines." (PMID 31936903, 2020). "Because we demonstrated that HDIs were able to induce EMT and autophagy in which FOXO1 played a key role, a FOXO1 inhibitor, when combined with HDIs, might be a promising therapeutic approach for cancer." (PMID 32929346, 2020). "The oestrogen-activated ER has been shown to interact with FOXO1 to repress its activity, and it is speculated that this interaction may play a part in the regulation of cancer metastasis." (PMID 32372224, 2020). "Interestingly, forced expression of FoxO1 can induce apoptosis in certain cancer cell types, whereas in other cancer cell types, it can induce G1 cell cycle arrest through upregulation of the cyclin-dependent kinase inhibitor p2712,14." (PMID 32398756, 2020). "Finally, we assessed markers of cellular energy stress (pACC, ACC, FOXO1, and PGC1β) and cancer stem cell-ness (aldehyde dehydrogenase)." (PMID 32854297, 2020). "Activation of ERK kinases contributes to FOXO1 downregulation in various types of cancer cells." (PMID 32823589, 2020). "Moreover, LINC00511 was found to interact with a variety of signaling pathways including JAK2/STAT3, Wnt/β-catenin, and PTEN/AKT/FOXO1, in the pathogenesis of cancers." (PMID 32698787, 2020). "Several studies have shown that the activation of FOXO1 can induce apoptosis in cancer cells." (PMID 32704044, 2020). "The GEPIA database was used to evaluate the expression of FOXO1 in different cancers." (PMID 32047567, 2020). "After confirming the role of the FOXO1-autophagy pathway in HDI-mediated metastasis, we next investigated whether inhibition of FOXO1 potentiates the anti-cancer effects of HDCAIs in HCC." (PMID 32929346, 2020). "In conclusion, we identified new microRNA–mRNA interactions, such as miR-27a/Foxo1, miR-27a/Mef2c, miR-27b/Cxcl12, miR-27b/Mef2c, miR-140/Cxcl12, miR-199a/Cav1, and miR-199a/Junb, that may contribute to muscle wasting in cancer cachexia." (PMID 31013615, 2019). "The discovery of a novel function of FOXO1 in HDACIs-mediated autophagy in human cancer cells may support the development of a novel combinatorial anticancer therapeutic strategies leveraging on a potential synergy between HDACIs and inhibitors of SESNs." (PMID 31546746, 2019). "In line with this speculation, we first observed that the cell abilities of cancer stemness, migration and invasion were obviously restored after c-Myc was transfected into FOXO1-overexpressing NPC cells." (PMID 31754475, 2019).
cancer (continued). "FOXO1 has been shown to be a protein involved in the dynamic control of autophagy, which might be essential for maintenance of autophagic flux in cancer cells and neurons." (PMID 31186406, 2019). "Specifically, our results suggest that microRNA/mRNA interactions miR-27a/Foxo1, miR-27a/Mef2c, miR-27b/Cxcl12, miR-27b/Mef2c, miR-140/Cxcl12, miR-199a/Cav1, and miR-199a/Junb may contribute to muscle wasting in cancer cachexia." (PMID 31013615, 2019). "In light of these findings, numerous research has proposed that regulating FoxO1 could be applied in cancer therapy." (PMID 31767027, 2019). "We sought to determine whether EZH2 regulation of FOXO1 expression plays any role in the anti-cancer effect of EZH2 inhibitor." (PMID 31410199, 2019). "Next we examined whether upregulation and nuclear localization of FOXO1 play any roles in the death of PTEN-negative cancer cells co-treated with GSK126 and DTX." (PMID 31410199, 2019). "The connection between the differential anti-cancer efficacies of EZH2 inhibitor in PTEN-positive versus PTEN-negative cancer cells with FOXO1 protein induction and cellular localization further highlights the essential role of FOXO1 in EZH2 inhibitor-induced death of cancer cells." (PMID 31410199, 2019). "We further predicted new microRNA–mRNA interactions, such as miR-27a/Foxo1, miR-27a/Mef2c, miR-27b/Cxcl12, miR-27b/Mef2c, miR-140/Cxcl12, miR-199a/Cav1, and miR-199a/Junb, which may contribute to muscle wasting in cancer cachexia." (PMID 31013615, 2019). "Thus, our findings uncover a molecular module that links the role of FOXO1 to the action of EZH2 inhibitor in cancer." (PMID 31410199, 2019). "Moreover, western blot analysis revealed that the treatment of GSK126 also upregulated the protein level of FOXO1 in these cancer cell lines." (PMID 31410199, 2019). "The function of FOXO1 in the chemoresistance in cancer cells has been evaluated in vitro." (PMID 31400752, 2019). "Moreover, we showed miR-145a as a new potential FoxO1 regulator during muscle wasting in cancer cachexia." (PMID 31013615, 2019). "These genes contain known cancer-related genes such as Jak3, Foxo1, and Cdkn1a (p21)." (PMID 30621584, 2019). "Forkhead box O1 (FOXO1), a member of forkhead family, has been reported to regulate carcinogenesis by activating or suppressing the expression of its target genes in various human malignant tumors." (PMID 30406026, 2018). "As we know, oxidative stress generated by treatment of cells with H2O2 can activate the expressions of Foxo transcription factors (like Foxo1, Foxo3a, and Foxo4), which may interact with β-catenin to inhibit the apoptosis of cancer cells." (PMID 30627375, 2018). "FOXO1 downregulation is known to be involved in cancer progression in some human malignancies." (PMID 30406026, 2018). "However, we observed straight accumulation of FoxO1 protein under NaB treatment in time dependent manner in HCT-116 and A-549 cancer cells with Ras mutation." (PMID 31435511, 2018). "It was reported that FOXO1 is a negative regulator in various types of cancers." (PMID 30618730, 2018). "Cancer cells showed increased levels of FOXO1 expression compared to benign esophageal cells." (PMID 30478420, 2018). "Similarly, ectopic miR-126 has been proposed to downregulate IRS1, reduce AKT signaling and inhibit cytosolic sequestration of FOXO1 in response to mitochondria-destabilizing stimuli involved in cancer induction and progression." (PMID 27999212, 2017). "Curcumin exhibits its anticancer effects against different types of cancer by targeting multiple therapeutically important cancer signaling pathways such as Ras, mTOR (mammalian target of rapamycin), FOXO1 (forkhead box protein 1), Wnt/β-catenin, PI3K (phosphoinosmde-3-kinase) and AKT pathways." (PMID 27738325, 2016).
cancer (continued). "Previously, we also underlined that increased expression of GNA13 could accelerate the G1/S phase transition, thereby promoting cancer cell proliferation and tumorigenesis probably due to modulation of c-Myc and FOXO1 activity." (PMID 27883022, 2016). "Our results suggest that miR-495 could regulate the protein levels of Foxo1, p27kip1, p21Cip1, and Cyclin D1, all of these genes are downstream of Akt1, and subsequently inhibit cancer cell growth by promoting cell cycle arrest." (PMID 27323412, 2016). "Moreover, FoxO1 shows the most abundance in insulin-responsive tissues (e.g., liver) and its dysregulation has been found in several human cancers." (PMID 26893361, 2016). "Dissection of the target genes of Foxo1 and Foxo3 under DR conditions might reveal precise pathways that regulate cancer and aging in mammals." (PMID 25808402, 2015). "FOXO1 has been shown to be a target of regulation by many cancer-related miRNAs." (PMID 25739100, 2015). "Accumulating data suggest that FOXO1 is downregulated in various types of cancers." (PMID 25888950, 2015). "However, to promote cancer activity, they also target different genes including C/EBPβ, FOXO1, NFI-A, STAT5A, ARTN, FBXW7, and SEPT6 (for miR-223) and FUS1, RhoC, PTEN, CDKN1A, TGFβR2, and NRF2 (for miR-93)." (PMID 26273679, 2015). "For instance, FOXO1 acts as a tumor suppressor which could induce apoptosis and cell cycle arrest in cancer cells." (PMID 25010679, 2014). "As Foxo1 is an investigative cancer therapy target, the development of Foxo1 interventions may assist the quest to specifically suppress or activate HIV-1 replication in vivo." (PMID 25330112, 2014). "Moreover, FoxO1 is also upregulated in skeletal muscle of human cancer patients, and was recently identified as a cachexia-associated gene." (PMID 25539728, 2014). "Further investigation of the interplay between FoxO3a and FoxO1 in benign and cancer cells, and among different cancer cells will not only advance the understanding of autophagy regulation but may also provide information for targeting autophagy in therapy." (PMID 25546383, 2014). "Inactivation of FOXO1 has been documented in many types of human cancer." (PMID 24864265, 2014). "Besides working as a transcription factor, cytoplasmic FOXO1 binds and activates the autophagy-regulating protein, Atg7 and is involved in stress-induced autophagy in cancer cells, which results in anti-neoplastic effect." (PMID 23874926, 2013). "Therefore, modulating FOXO1 expression has been suggested to lead to the development of new therapeutic treatments for certain types of cancer." (PMID 23946796, 2013). "Notably, FOXO1 has been identified as a pioneer factor in cancer cells." (PMID 41282062, 2025). "Hence, while arzanol inhibits SIRT1 in hippocampal tissue with resultant effects on FOXO1 signaling, the consequences of this same molecular interaction in cancer cells may differ." (PMID 41304625, 2025). "It has been shown that FOXO1 contributes to the development of gastric and epithelial ovarian cancers, regulates cellular metabolic reprogramming in response to intrinsic or extrinsic stress, as well as controls cancer cell apoptosis through the regulation of target genes." (PMID 41124013, 2025). "These include suppressing adipogenesis through the repression of the Akt-FOXO1-PPARγ axis, significant cytotoxicity against nine tested cancer cell lines, notable antifeedant activity tested against Reticulitermes speratus, and cytotoxicity against human cancer cell lines." (PMID 38379969, 2024). "FOXO1 is a transcription factor that plays a role in regulating cellular growth and apoptosis; its inactivation or loss of function in CRC can allow the evasion of such processes, allowing cancer cells to escape programmed cell death and continue proliferating." (PMID 38891994, 2024). "However, in cancer cells, the activity of FOXO1 and FOXO3 is often dysregulated." (PMID 38994962, 2024).